METRN (meteorin, glial cell differentiation regulator)
Description:
Involved in both glial cell differentiation and axonal network formation during neurogenesis. Promotes astrocyte differentiation and transforms cerebellar astrocytes into radial glia. Also induces axonal extension in small and intermediate neurons of sensory ganglia by activating nearby satellite glia (By similarity).
Synonyms: C16orf23; MGC2601; c380A1.2
Tractability: Antibody: UniProt places it where antibodies can reach, with medium confidence; UniProt predicts a signal peptide or a membrane-spanning region; its Gene Ontology location is reachable by antibodies, with medium confidence.
Gene: Protein-coding gene on chromosome 16 (715,118 to 719,655, forward strand). Ensembl gene ENSG00000103260.
Subcellular location: Secreted
Subcellular location (Human Protein Atlas): Nuclear membrane; Cytosol; Nucleoplasm; Predicted to be secreted
Gene Ontology:
Molecular function: hormone activity
Biological process: glial cell differentiation; positive regulation of axonogenesis; signal transduction
Cellular component: extracellular region
Genetic constraint (gnomAD): Loss-of-function variants: 18 observed, 8.21 expected, observed/expected ratio (o/e) 2.19. That is too few expected variants to judge how well the gene tolerates losing a copy. Missense variants: 489 observed, 301.03 expected, observed/expected ratio (o/e) 1.62, 90% interval 1.51 to 1.75. Synonymous variants: 230 observed, 142.86 expected, observed/expected ratio (o/e) 1.61, 90% interval 1.45 to 1.79.
Homologues: Orthologues: chimpanzee METRN (99% identical), macaque METRN (93% identical), guinea pig METRN (81% identical), mouse Metrn (81% identical), pig METRN (73% identical), rat Metrn (65% identical), zebrafish metrn (48% identical). Paralogues in human: METRNL (43% identical).
Diseases named in the same sentence as METRN in open-access papers:
METRN is named in the same sentence as 9 diseases in open-access papers, as found by Europe PMC text mining. Sharing a sentence is not in itself a finding about the gene and the disease. The quoted sentences say what the papers report.
glioblastoma (5 papers, 2021 to 2024). The most malignant astrocytic tumor (WHO grade IV). "This study emphasizes the significance of exosomal circ-METRN in glioblastoma progression and radioresistance." (PMID 38312628, 2024). "Low-dose radiation stimulates GBM cells to secrete circ-METRN-rich SEVs, and circ-METRN enhances glioblastoma progression and radioresistance by regulating the miR-4709-3p/GRB14/PDGFRα pathway." (PMID 35999601, 2022). "The ldrEXOs-derived circ-METRN enhanced the glioblastoma progression and radioresistance via miR-4709-3p/GRB14/PDGFRα pathway." (PMID 33867829, 2021). "Glioblastoma patients displaying high levels of exosomal circ-METRN exhibited a worse prognosis than other groups." (PMID 33867829, 2021). "Meanwhile, serum exosomal circ-METRN can also assist MRI diagnosis in the early detection of recurrence in glioblastoma patients." (PMID 33867829, 2021). "After microarray analysis for ldrEXOs, a total of 23 circRNAs, including circ-METRN, were identified as abnormally expressed in glioblastoma exosomes." (PMID 33867829, 2021). "Then, we rediagnosed glioblastoma recurrence using a novel method combining MRI with serum exosomal circ-METRN (detected in the early stage of radiotherapy)." (PMID 33867829, 2021). "Inhibition of GRB14 attenuated the tumor-promoting function of ldrEXOs although circ-METRN was highly expressed in glioblastoma cell lines previously treated with ldrEXOs." (PMID 33867829, 2021). "The mechanism of low-dose radiation-induced exosomal circ-METRN via miR-4709-3p/GRB14/PDGFRα pathway in glioblastoma cells was elucidated by using the schematic cartoon." (PMID 33867829, 2021). "This tumor-promoting effect of low-dose radiation-induced exosomal circ-METRN enables it to be an effective biomarker and a therapeutic target for glioblastoma patients with poor prognosis." (PMID 33867829, 2021). "Despite the low expression of miR-4709-3p in glioblastoma, the sponging effect of the ldrEXO-transported circ-METRN was still observed." (PMID 33867829, 2021). "ldrEXOs with high levels of circ-METRN, instead of ldrEXOs_siCIRC (ζ), also rescued proliferation, radioresistance, apoptosis resistance, invasion, and migration abilities of glioblastoma cell lines previously treated with high-dose radiation (HDR) (ε)." (PMID 33867829, 2021). "Detection of circ-METRN expression levels in serum SEVs of patients with glioma early in radiation therapy not only helps to predict radioresistance and prognosis but also assists in the early detection of glioblastoma recurrence by MRI." (PMID 35999601, 2022). "However, ldrEXOs with inhibition of circ-METRN (ldrEXOs_siCIRC) did not significantly exhibit the promoting effect, suggesting the important role of exosomal circ-METRN in the DNA damage-repair process in glioblastoma cells." (PMID 33867829, 2021). "ldrEXOs promoted proliferation, radioresistance, apoptosis radioresistance, invasion, and migration abilities of glioblastoma cell lines (β) while knockdown of circ-METRN (γ) or up-regulation of miR-4709-3p (δ) attenuated these abilities of glioblastoma cell lines previously treated with ldrEXOs." (PMID 33867829, 2021). "To verify whether exosomal circ-METRN can still play a sponging role in the high level of miR-4709-3p, we also observed the effect of ldrEXO treatment on the miR-4709-3p level in glioblastoma cells treated with the previous transfection of miR-4709-3p mimics." (PMID 33867829, 2021). "Taken together, low-dose radiation-induced exosomal circ-METRN may exert its positive regulatory functions in glioblastoma progression and radioresistance via miR-4709-3p/GRB14/PDGFRα pathway." (PMID 33867829, 2021). "It has important clinical values to detect the serum exosomal circ-METRN in the early stage of radiotherapy, which is not only conducive to predict radioresistance and prognosis but also to assist MRI diagnosis in detecting the very early recurrence of glioblastoma." (PMID 33867829, 2021).
glioblastoma (continued). "Therefore, the regulatory function of ldrEXOs in glioblastoma may depend on exosomal circ-METRN, and exosomal circ-METRN exerts its regulatory functions in promoting glioblastoma progression and radioresistance through sponging miR-4709-3p." (PMID 33867829, 2021). "The relative expression levels of circ-METRN and its cognate linear mRNA before and after treatment with Rnase R were also analyzed in NHA and glioblastoma cell lysates." (PMID 33867829, 2021). "We identified the role of low-dose radiation-induced exosomal circ-METRN and miR-4709-3p/GRB14/PDGFRα pathway, bringing a novel insight into the investigation of exosomal circRNAs and providing potential targets for anti-glioblastoma therapy." (PMID 33867829, 2021). "Moreover, ldrEXOs with high levels of circ-METRN rescued tumor-growth ability of glioblastoma previously treated with HDR while ldrEXOs_siCIRC did not significantly exhibit the rescue effect." (PMID 33867829, 2021).
glioma (2 papers, 2019 to 2021). A benign or malignant brain and spinal cord tumor that arises from glial cells (astrocytes, oligodendrocytes, ependymal cells). "Then, the expression level of circ-METRN in different grades of glioma tissues was proved to be very different." (PMID 33867829, 2021). "This study aimed to investigate the role of hsa_circ_0037251, one circRNA generated from several exons of the gene termed METRN, in glioma progression." (PMID 31875034, 2019).
colorectal cancer (1 paper, 2020). A primary or metastatic malignant neoplasm that affects the colon or rectum. "We aimed to explore the relationship between METRN and colorectal cancer (CRC) prognosis." (PMID 31859449, 2020).
melanoma (1 paper, 2025). A malignant, usually aggressive tumor composed of atypical, neoplastic melanocytes. "We found that CENPF, E2F3, KIRREL, METRN were both upregulated and associated with worse OS in melanoma patients." (PMID 40299364, 2025).
preeclampsia (1 paper, 2015). Preeclampsia is a hypertensive disorder of pregnancy that is characterized by new-onset hypertension with proteinuria presenting after 20 weeks of gestation, and depending on mild or severe forms may initially present with severe headache, visual disturbances, and hyperreflexia. "Thus, it is plausible to hypothesize that reduced METRN levels contribute to the risk of preeclampsia characterized by reduced placental vascular development, leading to poor placental function and fetal growth compromise." (PMID 26121675, 2015). "Since METRN is a secreted protein that attenuates angiogenesis in astrocytes, we hypothesized that circulating METRN levels might be altered during normal pregnancy and preeclampsia." (PMID 26121675, 2015).
retinal (1 paper, 2022). "During retinal neurodegeneration, circular RNA-ZNF609 overexpression leads to the sink of miR-615 and removes the miR-615-mediated inhibitory role on METRN expression." (PMID 34569008, 2022).
endocrine diseases (1 paper, 2020). "In recent years, METRN and the meteorin‐like (METRNL) protein, which is homologous to METRN, have been implicated as biomarkers of hematological and endocrine diseases." (PMID 31859449, 2020).
tumor (1 paper, 2021). "In the present study, ldrEXOs-derived circ-METRN played a key role in the tumor progression and radioresistance while ldrEXOs with knockdown of circ-METRN did not exhibit a similar tumor-promoting function." (PMID 33867829, 2021).
METRN also shares sentences with these, for which no sentence is quoted: breast carcinoma (2 papers).